EGF (epidermal growth factor)
Diseases named in the same sentence as EGF in open-access papers (continued):
Sharing a sentence is not in itself a finding about the gene and the disease.
tumor (continued). "The tumour-associated microglia and macrophages (TAMs) present in the GB tumour microenvironment release growth factors and cytokines, including EGF (Epidermal Growth Factor) and CSF-1, which can promote tumour proliferation, survival and invasion." (PMID 37803333, 2023). "M2 macrophages similarly release growth factors, such as vascular endothelial growth factor (VEGF), epidermal growth factor (EGF), and fibroblast growth factor (FGF), which promote tumour cell proliferation, invasion, and metastasis." (PMID 38130720, 2023). "Continuous stimulation with EGF and HGF leads to ligand‐based activation of signalling pathways as is occurring in the tumour." (PMID 37679999, 2023). "M2 macrophages secrete epidermal growth factor (EGF), matrix metalloprotein 9 (MMP-9) and the anti-inflammatory factor IL-10 to promote tumor progression." (PMID 36969211, 2023). "EGF is an upstream regulator of PI3K/AKT signaling pathway and plays an important role in tumor metastasis." (PMID 36594087, 2023). "We next examined the role of EGF‐induced and c‐Src‐upregulated CD47 expression in tumorigenesis and tumor immune evasion in mice." (PMID 37541303, 2023). "For the first time we demonstrated that TAMs’ scavenger receptor stabilin-1 is responsible for the clearance of epidermal growth factor (EGF), a potent stimulator of tumor growth." (PMID 36960065, 2023). "M2 macrophages secrete EGF, matrix metalloprotein 9 (MMP-9), and other proteins to suppress antitumor effects and promote tumor progression." (PMID 36843929, 2023). "CAFs can secrete specific biological factors such as EGF, TGF-β, and IL6 to facilitate tumor malignant phenotype, including tumor neovascularization and immune escape, leading to tumor deterioration." (PMID 36755806, 2023). "M2-type macrophages interact with tumor cells by releasing EGF, MMPs, VEGF, and TGFβ, thus promoting tumor proliferation, invasion, angiogenesis, and immune escape." (PMID 37415251, 2023). "Platelets promote tumor growth by secreting various growth factors such as VEGF, TGF-β, platelet-derived growth factor, and epidermal growth factor." (PMID 36789987, 2023). "Platelet-derived growth factor (PDGF) signaling, besides other growth factor-mediated signaling pathways like vascular endothelial growth factor (VEGF) and epidermal growth factor (EGF), seems to play a crucial role in tumor development and progression." (PMID 36264073, 2022). "For example, tumor-produced M-CSF stimulates TAM production of epidermal and vascular endothelial growth factor (EGF and VEGF), which activate tumor cells in a paracrine loop to promote extravasation and enhance metastasis." (PMID 34876704, 2022). "In concordance with a role for the tumor microenvironment and the EGFR pathway more specifically, our group reported that the strong activation of EGFR by EGF resulted in EMT induction with an up‐regulation of SNAIL, SLUG, and ZEB1." (PMID 34382739, 2022). "The MEK-ERK signaling pathway mediates the tumor microenvironmental EMT-inducing mitogenic signals, such as EGF, FGF, extracellular HSP90, and extracellular vesicles (EVs)." (PMID 36552758, 2022). "Resident and infiltrating TAMs are recruited to the growing tumor in response to a variety of tumor-secreted cytokines, including CCL2, GM-CSF, EGF, CXC3CL1, SDF-1, and CSF-1." (PMID 35885058, 2022). "EGF induces EMT in cancers through the EGF/EGFR signaling pathway, thus promoting the invasion and metastasis of tumor cells." (PMID 35526240, 2022). "By modulating epidermal growth factor (EGFR) activation, SPP1 can influence the immune escape and malignant biological activity of tumor cells, and its overexpression enhances HCC development and metastasis." (PMID 36353638, 2022). "According to the anti-tumor function of PPAR-γ and the anti-apoptotic function of IGF system, MAPK activation by various growth stimuli such as insulin, IGF, epidermal growth factor (EGF), and platelet-derived growth factor (PDGF) may cause serine phosphorylation of PPAR-γ." (PMID 36291082, 2022).
tumor (continued). "Flexible short peptides, composed of GGGGS, were also used to construct a Gel fusion with epidermal growth factor (EGF), the receptor of which (EGFR) is overexpressed on the surface of tumor cells." (PMID 35744957, 2022). "Bone marrow-derived suppressive cells infiltrate the primary tumor and induce EMT in tumor cells through the TGF-β, EGF, and HGF signaling pathways, leading to metastasis and the spread of tumor cells." (PMID 36119037, 2022). "TAMs also facilitate tumor-cell growth and angiogenesis by generating various types of growth factors, including transforming growth factor-β (TGF-β), epidermal growth factor (EGF), and vascular endothelial growth factor (VEGF)." (PMID 35799889, 2022). "When combined with ligand-EGF, EGFR can phosphorylate tyrosine residues, activate EGFR, and promote the growth and proliferation of tumor cells." (PMID 35310032, 2022). "For instance, NANOG was a major transcription factor that enhances secretory autophagy in tumor cells via promoting LC3B expression, leading to EGF autocrine." (PMID 36300110, 2022). "CAFs assist tumor growth and dissemination through the production of factors such as EGF, IL-6, TGF-β, and VEGF, which promote tumor cell proliferation and angiogenesis." (PMID 36010693, 2022). "PAI-1 expression in the TME is regulated by growth factors, cytokines and hormones including EGF and TGF-β via different, perhaps tumor-specific, pathways." (PMID 35267539, 2022). "These stromal tumor cells also showed stimulation with several growth factors, such as PDGF, VEGF, EGF, and IGF, and activated downstream signals." (PMID 35664733, 2022). "Stimulation with EGF or GAS6 enhanced downstream signaling in parental EGFRMT cells, and EGFR and MERTK shared common signaling pathways that promote tumor cell survival and proliferation, including PI3K/AKT and MAPK/ERK pathways." (PMID 35708914, 2022). "In this regard, we evaluated the expression of SOX2 in blood mononuclear cells expressing tumor markers such as AXL, EGF, CD87, CD90, or CD276." (PMID 36142766, 2022). "In the TME, TAMs participate in tumor angiogenesis by releasing growth factors such as CCL2, CXCL8, CXCL12, EGF, IL-1β, IL-8, PIGF, TGF-β, and VEGF-A." (PMID 36105288, 2022). "Both cetuximab and panitumumab compete with epidermal growth factor (EGF) for binding to perturb the downstream signaling of EGFR, thus inhibiting the proliferation of tumor cells." (PMID 35907884, 2022). "TGF-β, in turn, further activates fibroblasts to provide tumor prosurvival signals, including elevated expression of ITGA5, while promoting ECM production and upregulation of EGF to maintain persistence of the signaling loop." (PMID 35267539, 2022). "GBM3, an established primary GBM cell line, as well as U251, can successfully form tumour spheres and continue to grow in the modified NSC medium containing EGF." (PMID 36116131, 2022). "Comparing MDA-MB-231, Hs578T and EGF-treated MDA-MB-468 cells silenced for CD44 in vitro, we observed a clear diminution of human tumor cell content in lungs 24 h after injection." (PMID 35805061, 2022). "ALDH1A1 maintains self‐renewal of CrT/TICs and facilitates the expression and secretion of EGF from CrT/TICs, which subsequently promotes the activation of EGFR signalling in differentiated cancer cells and tumour growth of LUSC." (PMID 36504325, 2022). "While treatment of GBM cells with either EGF or IFN-γ induces the expression of GBP-1, only EGF treatment induces the expression of matrix metalloproteinase 1 (MMP1) and promotes tumor cell migration/invasion." (PMID 35681772, 2022). "In tumor cells, GFs like TGF-β, EGF, or Notch proteins regulate the expression of E-cadherin repressors to maintain their stem cell-like phenotype." (PMID 35158804, 2022). "In TMEM, TAMs can produce EGF (epidermal growth factor) and secrete chemokine CCL18, and tumor cells can also secrete chemokine CCL18 and produce cytokine CSF-1, all of which play important roles in the process of tumor cell invasion." (PMID 36131942, 2022).
tumor (continued). "These TIMs then release a wide array of factors, such as matrix metalloproteinases, IL-10, epidermal growth factor (EGF), vascular endothelial growth factor (VEGF), and IL-17, which are involved in the stimulation of proliferation and migration of tumor cells." (PMID 35884700, 2022). "EGF is a chemokine in the TME, which can accelerate tumor metastasis by promoting the migration and invasion of tumor cells." (PMID 36105288, 2022). "It was revealed that stimulation with EGF induced the dissociation of E-cadherin complexes from actin, stressing the role of EGFR signaling in cell–cell adhesion and tumor progression." (PMID 35216384, 2022). "The number of tumor cells with phenotype CD87+CD117+, CD117+Axl+EGF+CD44+, EGF+Axl+, CD117+EGF+, CD276+CD117+, and EGF+Axl− had a tendency to increase." (PMID 36142766, 2022). "Meanwhile, macrophages release epidermal growth factor (EGF), which enhances tumor cell invasion and migration, and further stimulates tumor cells to secrete CSF-1, thus forming a positive feedback loop between tumor cells and macrophages." (PMID 35965509, 2022). "CD82 can weaken the EGF/EGFR induction signal and inhibit tumor metastasis, but the mechanism is still unclear." (PMID 35538033, 2022). "It has been shown that LEC-derived factors promote MCF-7 and tumor growth, and these effects are driven by growth factors PCGF-BB and EGF." (PMID 35806196, 2022). "According to our analysis, the way to overcome these issues is to use growth factors (EGF, FGF, and B27) and cultivate stem cells with tumor proliferative capacity in serum-free media." (PMID 35406768, 2022). "Alternatively, one study has reported that exogenous EGF can stimulate the expression of NTN4, a regulator of GBM tumor progression/proliferation via ITGB4-Akt signal activation." (PMID 36316307, 2022). "Mechanistically, TAMs can produce cytokines such as VEGF, EGF, platelet-derived growth factor (PDGF) to promote tumor angiogenesis, and matrix metalloproteinases secreted by TAMs can remodel TME to facilitate tumor metastasis." (PMID 36093115, 2022). "EGF-secreted TAMs also increased the invasive and migratory capacity of SKOV3 cells isolated from in vitro 3D spheroids, generated by TAMs and tumor cells." (PMID 35682890, 2022). "Here, we show that ERK5 inhibition or silencing decreased EGF-induced EC cell proliferation, and that genetic deletion of MEK5 resulted in EC impaired proliferation and reduced tumor growth capacity in nude mice." (PMID 36123565, 2022). "EGF subsequently upregulated the EGFR-AKT signaling pathway and then led to tumor cell resistance to CTL killing." (PMID 36300110, 2022). "The omega- 3 fatty acids EPA and DHA have been shown to inhibit tumor growth induced by TPA and epidermal growth factor (EGF)." (PMID 36290833, 2022). "In many tumours, molecules such as hepatocyte growth factor (HGF), epidermal growth factor (EGF), platelet-derived growth factors (PDGF), and TGF-β can act as epithelial-mesenchymal transformation (EMT)-inducible signals." (PMID 36338118, 2022). "Since miR-223 then targets EGF expression, Palbociclib treatment eventually results in autocrine and paracrine dampening of EGFR pathway in tumor cells as well as in the tumor microenvironment." (PMID 35712501, 2022). "Multiple lines of evidence suggest induced expression of EGF and TGF-alpha in early-stage hepatocarcinogenesis, demonstrating the possible role of MAPK/ERK pathway in tumor progression of hepatocytes." (PMID 35897659, 2022). "PGE2 promotes tumor cell EMT and invasion by interacting with oncogenic signals, including epidermal growth factor (EGF) and epidermal growth factor receptor (EGFR)." (PMID 35936717, 2022). "(C) Immunohistochemistry analysis of the expression of EGF and RAD51 in control and METTL3-KD tumor tissues." (PMID 35502895, 2022). "Compared with DOX alone, EGF@DOX-NPs significantly decreased the viability and migration and enhanced the apoptosis rates of tumor cells in vitro." (PMID 35156493, 2022).
tumor (continued). "PPI analysis revealed 22 genes for MECa and 63 for AdCC that were validated by Kaplan–Meier that showed FN1 and SPP1 for MECa, and EGF and ERBB2 for AdCC as more significant candidate genes for each neoplasm." (PMID 36146635, 2022). "EGFR ligands, such as EGF and transforming growth factor [TGF]α, reduce tumor antigen presentation through MHC class I and II expression, while EGF promotes M2 polarization of macrophages." (PMID 36439487, 2022). "The CELsignia test was performed on cell samples cultured from each patient tumor specimen to evaluate HER-family and c-Met signaling activity applying EGF, NRG, and HGF agonists." (PMID 34998412, 2022). "As the difference in basal and EGF-induced FAK activation between the cell lines was highly significant, we suspected this was a major mechanism whereby integrin β1 regulates tumor cell growth and proliferation." (PMID 35763345, 2022). "EGF can induce STAT3 activation and block the interaction between STAT3 and EGFR, which can inhibit tumor growth." (PMID 35547655, 2022). "M2 macrophages can stimulate tumor growth angiogenesis, metastasis by secreting a variety of inflammatory factors such as TGF-β, platelet-derived growth factor, and epidermal growth factor." (PMID 36569220, 2022). "To test whether exogenous administration of cholesterol can also influence cell plasticity and possibly tumor initiation, we cultured primary murine acinar explants in a synthetic matrix scaffold and ductal metaplasia was induced by the addition of recombinant EGF." (PMID 33652890, 2021). "These matrices are then supplemented with tumor-selective medium containing a well-defined mix of growth factors, such as R-spondin (RSPO), WNT3A, epidermal growth factor (EGF) and bone morphogenetic proteins (BMP) inhibitor Noggin." (PMID 34957115, 2021). "M2-polarized TAMs in close proximity of OSCC cells can induce the migration and invasion of the latter, via activation of NF-kB and favor the production of growth factors (e.g., EGF and TGF-β) that promote tumor progression." (PMID 33816242, 2021). "Thus, our model predicts that administering EGFR-targeted drugs soon after tumor removal surgery can instead stimulate cancer cells to proliferate and to form new colonies in cooperation with internal molecules of EGF, which level may be increased following surgery." (PMID 33748471, 2021). "Studies have shown that cytokines hepatocyte growth factor (HGF), epidermal growth factor (EGF), etc can enhance the phosphorylation of cortactin, promoting the tumour metastasis." (PMID 33191645, 2021). "PDK1 knockdown repressed EGF-induced tumor cell transformation, and the downregulation of PDK1 expression or inhibition of its activity significantly blocked EGF-enhanced cell migration and invasion." (PMID 33739396, 2021). "Activated JNK increased the secretion of epidermal growth factor (EGF) or stromal cell-derived factor 1 (SDF-1/CXCL12), thereby increasing invasion of tumor cells and metastasis." (PMID 34207247, 2021). "After EGF exposure, the fraction of EGFR colocalizing with EEA1 increased for both tumor cell lines." (PMID 34572731, 2021). "We show here that the tumour suppressor CYLD is essential for CME of EGFR and its lysosomal degradation is induced by EGF and CTX in HNSCC cells." (PMID 35008337, 2021). "Here, TAMs within the spheroids secrete epidermal growth factor (EGF) and lead to upregulation of integrin and intercellular adhesion molecule 1 (ICAM‐1) in tumor cells." (PMID 34060699, 2021). "Via a plethora of substrates, WWP1 regulates kaleidoscopic signaling pathways such as TGFβ, EGF, WNT, PI3K-AKT, and Hippo pathways, consequently promoting or inhibiting neoplasia and progression of diverse cancers." (PMID 34712671, 2021). "Although the expression of EGF declines with age, the use of IPC should be regulated properly in order to avoid the pathogenesis of tumor." (PMID 34830467, 2021).
tumor (continued). "Epidermal growth factor (EGF) and EGF receptor (EGFR) signaling play critical roles in tumor growth." (PMID 34405016, 2021). "EGF was also observed to increase αMβ2 integrin on TAMs and ICAM-1 on tumor cells, promoting the adhesion between TAMs and tumor cells." (PMID 34717710, 2021). "MSCs exposed to PDAC cells are activated into CAF-secreting tumor-promoting proteins such as hepatocyte growth factor (HGF), epidermal growth factor (EGF), and interleukin-6 (IL-6)." (PMID 33803229, 2021). "It concerns particularly cancer-associated fibroblasts (CAFs), which produce several growth factors, e.g., EGF (epidermal growth factor) and HFG (hepatocyte growth factor) that promote tumor growth and progression." (PMID 33921525, 2021). "In this study, we demonstrate that MDSCs are a source of milk fat globule-epidermal growth factor (EGF) factor 8 (MFGE8), which is known to be involved in tumor metastasis." (PMID 34440100, 2021). "Several studies showed that miRNAs can regulate tumour angiogenesis through targeting both the pro- and antiangiogenic factors, such as RTK signalling protein, HIF, VEGF, and epidermal growth factor (EGF)." (PMID 33761051, 2021). "The tumor cell-derived CCL2 transforms monocytes into M2-like macrophages, resulting in the increased production of EGF, which activates EGFR signaling in the tumor cells promoting the formation of invadopodia associated with increased HNSCC cell motility." (PMID 33925575, 2021). "High-resolution confocal microscopy has characterized actin cell protrusion formation and function in response to tumor-resembling ECM stiffness and soluble EGF stimulation." (PMID 34440749, 2021). "EGF binds with EGFR, thus activating the epidermal growth factor receptor, activating PI3K/Akt pathway, and finally promoting tumor proliferation." (PMID 33688358, 2021). "Tumor cells can secrete different pro-angiogenic factors, such as VEGF, FGF-2 and EGF, among others, capable of promoting the migration of endothelial cells and the formation of blood vessels." (PMID 33572239, 2021). "Studies indicate that complex extracellular and intracellular signaling pathways, including the epidermal growth factor (EGF)/mTOR, NF-κB/STAT3 and JNK pathways, are activated during tumor cell transformation, as promoted by chronic inflammation." (PMID 33921049, 2021). "Mice treated with EGF-conjugated HAOA-coated GNPs and 5 min laser exposure showed an average tumor reduction of 81.1 ± 12.6%." (PMID 33808293, 2021). "For instance, CAFs secrete growth factors such as CXCL12, HGF, EGF, IGF, IL‐6, IL‐8, IL‐11 and CCL5, which facilitate tumour growth." (PMID 33943003, 2021). "As a result of the hypoxia, these macrophages are then fine-tuned to express multiple protumorigenic cytokines and growth factors such as EGF and VEGF, promoting tumor vascularization and growth, resulting in increased metastases and worse survival." (PMID 34298638, 2021). "Vascular endothelial growth factor A (VEGFA) is one of the main mediators of angiogenesis, secreted by tumor cells, together with platelet-derived growth factor (PDGF), and epidermal growth factor (EGF)." (PMID 34208346, 2021). "Along with this, curcumin also inhibits excessive TGFβ receptor signaling and EGF- and EGFR-mediated signaling pathway and remarkably controls epithelial-to-mesenchymal transition, metastasis, and tumor progression, respectively." (PMID 34485117, 2021). "The most promising results in this study were observed with the 5 min laser irradiation combined with EGF-conjugated HAOA-coated GNPs, which led to a tumor reduction of approximately 81%." (PMID 33808293, 2021). "PC-derived chemokine CXCL12 (SDF-1) can trigger the EGF/CSF-1 paracrine invasion loop to mediate the co-migration of TAM and tumor cells, after binding to its receptor CXCR4 on both TAMs and tumor cells (process ➁)." (PMID 34179005, 2021).